TIAM2 (TIAM Rac1 associated GEF 2)
Description:
Modulates the activity of RHO-like proteins and connects extracellular signals to cytoskeletal activities. Acts as a GDP-dissociation stimulator protein that stimulates the GDP-GTP exchange activity of RHO-like GTPases and activates them. Mediates extracellular laminin signals to activate Rac1, contributing to neurite growth. Involved in lamellipodial formation and advancement of the growth cone of embryonic hippocampal neurons. Promotes migration of neurons in the cerebral cortex. When overexpressed, induces membrane ruffling accompanied by the accumulation of actin filaments along the altered plasma membrane (By similarity). Activates specifically RAC1, but not CDC42 and RHOA.
Synonyms: TIAM-2; STEF
Tractability: PROTAC: ubiquitination databases record sites on it.
Gene: Protein-coding gene on chromosome 6 (154,832,697 to 155,257,723, forward strand). Ensembl gene ENSG00000146426.
Subcellular location: Cytoplasm; Cell projection, lamellipodium; Cell projection, filopodium; Cell projection, growth cone; Cell projection, neuron projection; Perikaryon
Subcellular location (Human Protein Atlas): Nucleoli fibrillar center; Nucleoplasm; Cytosol
Pathways (Reactome):
Signal Transduction: G alpha (12/13) signalling events; NRAGE signals death through JNK; RAC1 GTPase cycle
Metabolism: PPARA activates gene expression
Gene Ontology:
Molecular function: protein binding; guanyl-nucleotide exchange factor activity; GTPase activator activity
Biological process: positive regulation of axonogenesis; regulation of small GTPase mediated signal transduction; small GTPase-mediated signal transduction; intracellular signal transduction; signal transduction
Cellular component: cytosol; extracellular exosome; fibrillar center; nucleoplasm; cytoplasm; membrane; perikaryon; synapse; filopodium; growth cone; lamellipodium; neuron projection
Genetic constraint (gnomAD): Loss-of-function variants: 73 observed, 154.96 expected, observed/expected ratio (o/e) 0.47, 90% interval 0.39 to 0.57. The upper end of that interval is the gene's LOEUF score, 0.57, which puts it in group 2 of 6, group 1 being the genes least tolerant of losing a copy. Missense variants: 1,903 observed, 2,171.9 expected, observed/expected ratio (o/e) 0.88, 90% interval 0.84 to 0.91. Synonymous variants: 787 observed, 862.42 expected, observed/expected ratio (o/e) 0.91, 90% interval 0.86 to 0.97.
Homologues: Orthologues: chimpanzee TIAM2 (99% identical), macaque TIAM2 (98% identical), guinea pig TIAM2 (88% identical), rat Tiam2 (85% identical), mouse Tiam2 (84% identical), dog TIAM2 (83% identical), pig TIAM2 (54% identical), zebrafish tiam2a (50% identical). Paralogues in human: TIAM1 (36% identical), TRIO (14% identical), KALRN (13% identical), PLEKHG4B (12% identical), MCF2L (11% identical), MCF2 (10% identical), MCF2L2 (10% identical), PLEKHG4 (9% identical), ARHGEF40 (9% identical), SPATA13 (9% identical), PLEKHG1 (8% identical), VAV3 (8% identical), and 10 more.
Diseases named in the same sentence as TIAM2 in open-access papers:
TIAM2 is named in the same sentence as 34 diseases in open-access papers, as found by Europe PMC text mining. Sharing a sentence is not in itself a finding about the gene and the disease. The quoted sentences say what the papers report.
lung cancer (4 papers, 2016 to 2023). A malignant neoplasm involving the lung. "Recent studies showed that TIAM2 was frequently upregulated in various human malignancies such as liver cancer, lung cancer." (PMID 37393317, 2023). "For instance, it was recently reported that the A549 lung cancer cell line was dependent on the GEFs ARHGEF39, FARP-1, and TIAM-2 while the MDA-MB-231 and GFP-HER2-BM cells have a different GEF compliment and express Vav." (PMID 36861094, 2022).
liver cancer (3 papers, 2016 to 2023). An epithelial or non-epithelial malignant neoplasm that arises from the liver. "The Tiam1 ortholog STEF/Tiam2 was found to promote proliferation and invasion in liver cancer when overexpressed, and is therefore implicated in the pathogenesis of HCC." (PMID 27104658, 2016). "Results from clinical specimens and cellular and animal models have shown that the short form of TIAM2 (TIAM2S) functions as an oncogene in the tumorigenesis of liver cancer." (PMID 26763486, 2016).
pancreatic cancer (3 papers, 2023 to 2025). "Mechanistically, NSUN2-mediated m5C modification suppresses TIAM2 expression through YBX1, and disruption of the NSUN2/TIAM2 axis impairs the EMT, thereby slowing pancreatic cancer progression." (PMID 40114967, 2025).
hepatocellular carcinoma (2 papers, 2016 to 2020). A malignant tumor that arises from hepatocytes. "Transcriptomic analysis revealed that the expression of the host gene is concomitantly downregulated for several, including an oncogene implicated in metastasis of hepatocellular carcinoma, TIAM2." (PMID 32427329, 2020). "Our previous study showed that TIAM2 was overexpressed in a great majority (86%) of hepatocellular carcinoma (HCC) samples and significantly associated with TIAM1 overexpression." (PMID 26763486, 2016). "T‐cell lymphoma invasion and metastasis 2 (TIAM2) is a neuron‐specific protein that has been found ectopically expressed in hepatocellular carcinoma (HCC)." (PMID 26763486, 2016).
adult T cell leukemia (1 paper, 2024). "A newly characterized gene, T cell lymphoma invasion and metastasis 2 (TIAM2), is associated with super-enhancers in adult T cell leukemia/lymphoma (ALT) samples, but not in normal T cells." (PMID 39284807, 2024).
Anxiety (1 paper, 2019). Intense feelings of nervousness, tension, or panic often arise in response to interpersonal stresses. "The behavioral score of anxiety-like behavior of the adult males—but not females—yielded 5 significant correlations with Slc1a7, 9530052E02Rik, Itgb7, Tiam2, and Tspo (adjusted p = 0.048)." (PMID 30655507, 2019).
asthma (1 paper, 2025). "The significant findings of this work indicate that extreme high temperature increased Cma1 and Tiam2 expression, and extreme low temperature increased Sftpc and Nxnl expression in asthma, especially among pediatric populations." (PMID 40313552, 2025). "We observed that the pediatric asthma subjects in the extreme high temperature group exhibited higher expression of Tiam2 and Cma1, whereas Wfdc21, Cib3, and Sftpc expression were decreased." (PMID 40313552, 2025). "A previous study in children with severe asthma showed that high expression of Tiam2 was related to regulation of actin cytoskeleton and chemokine signaling pathway." (PMID 40313552, 2025). "Adult asthma subjects in the extreme temperature fluctuation group showed consistently decreased Wfdc21, Cib3, Gpr171, and Cttnbp2 expression, while increased Tiam2 and Cma1 expression." (PMID 40313552, 2025). "We then observed that the pediatric asthma subjects in high temperature exposure showed increased Tiam2 and Cma1 expression." (PMID 40313552, 2025). "In addition, asthma subjects in the extreme temperature fluctuation group showed decreased expression of Wfdc21, Cib3, Gpr171, and Cttnbp2, while Tiam2 and Cma1 expression increased." (PMID 40313552, 2025).
colorectal cancer (1 paper, 2025). A primary or metastatic malignant neoplasm that affects the colon or rectum. "In contrast, T-cell lymphoma invasion and metastasis 2 (TIAM2) facilitates colorectal cancer development by sustaining a pro-inflammatory microenvironment through serotonin-dependent immunoregulatory pathways." (PMID 41007799, 2025).
deafness (1 paper, 2023). An inherited or acquired condition characterized by the complete loss of the ability to hear from one or both ears. "Defects in the 30 shared genes are related to several pathologies, such as vision abnormalities (TMEM135), cancer (CDH6, FZD10, TIAM2), neuropsychiatric disorders (Tenm4, Pde4dip, Grid2), deafness (TFB1M), neutrophil disorders (VPS45) and others." (PMID 36902345, 2023).
diabetes (1 paper, 2019). "Coding polymorphisms in the consensus Chr 17 area included those linked to cancer (Fndc1, Tiam2, Zdhhc14 Has1), growth and development (Igf2r, Afdn, Tiam2, T2), immunology or diabetes itself via the energetic electron transfer chain (Tiam2, Pde10A) or basal thermal metabolism." (PMID 31661517, 2019).
endometrial carcinoma (1 paper, 2020). A malignant tumor arising from the epithelium that lines the cavity of the uterine body. "Here, we describe a novel mechanism leading to TIAM2 overexpression in ovarian and endometrial carcinoma, that involves formation of a new fusion transcript transcribed from a nearby promoter that is highly active in these tissue types." (PMID 33097743, 2020).
neuroblastoma (1 paper, 2015). Neuroblastoma (NB) is the most common solid, extracranial childhood tumor. "In particular, protein kinase A (PKA) dependent phosphorylation of Tiam2 activates the Rac GEF activity of Tiam2, which is a critical signaling pathway underlying dibutyryl cAMP (dbcAMP) induced neurite extension of neuroblastoma cells." (PMID 25879033, 2015).
skin papilloma (1 paper, 2021). A benign papillary neoplastic growth on the skin composed of epithelial cells and a fibrous stalk. "The MT repolymerization after nocodazole treatment was shown to stimulate TIAM2, which in turn activates RAC1 on the leading edge of skin papilloma cells, stimulating actin repolymerization and membrane protrusion." (PMID 34830827, 2021).
T-Cell Lymphoma (1 paper, 2017). "Based on these results and because of their novelty in this field, we further studied two targets that showed opposite effects on the barrier function: T-Cell Lymphoma Invasion And Metastasis 2 (TIAM2 - RhoGEF) and Synapse Defective1 (SYDE1 - RhoGAP)." (PMID 28860633, 2017).
cancer (15 papers, 2010 to 2024). A tumor composed of atypical neoplastic, often pleomorphic cells that invade other tissues. "T-lymphoma invasion and metastasis-inducing protein 2 (Tiam2) is required for signal transduction pathways involved in the regulation of cytokinesis and implicated in liver physiology and cancer development were found down regulated in Fkbp51 KO." (PMID 38167156, 2024). "Previous studies have also shown that TIAM2 enhances the proliferation, migration, and invasion of LC cells as TIAM2 is not only an important receptor tyrosine kinase effector for Rac1-dependent cell motility, but also can affect cancer cells via cancer-associated fibroblasts." (PMID 36142328, 2022). "To further investigate the impact of TIAM2 on NSUN2-induced cancer progression, we co-transfected siRNA (siTIAM2 or siCtrl) into vector control or NSUN2-overexpressing PC cells." (PMID 37393317, 2023). "Overall, the lipid metabolism-related gene TIAM2 is not only involved in osimertinib resistance, invasion, and migration of cancer cells but also contributes to M2-like TAM polarization in LUAD." (PMID 36142328, 2022). "Several investigators have previously reported the relevance of TRIO, NET1, ECT2 and TIAM2 in cancer metastasis and clinical prognosis." (PMID 32029704, 2020). "The short isoform of human TIAM2 has been shown to promote proliferation and invasion in various cancer cells." (PMID 32650570, 2020). "TIAM2 encodes a guanine nucleotide exchange factor that plays a role in activating RHO-GTPases, is an upstream regulator in the Rac pathway, and is involved in cellular proliferation, cellular migration, and invasion in multiple types of cancer." (PMID 38347632, 2024). "It has been demonstrated that TIAM2 could facilitate cancer cells proliferation and migration, thereby facilitating cancer progression." (PMID 37393317, 2023). "After further experimental validation, we confirmed that lipid metabolism-related gene TIAM2 could increase the tolerance of cancer cells to osimertinib, promote cell motility, and induce M2-like TAM polarization in LUAD." (PMID 36142328, 2022). "Super-enhancers have been found in genes involved in T-cell activation (IL2RA/CD25, CD30, and FYN) and known cancer genes (TP73, CCR4, TIAM2, NFATC1, NFATC2, and PIK3R1) in ATL cells." (PMID 38791169, 2024). "The Cancer Genome Atlas (TCGA) data analysis indicated that the gene expression of TRIO, NET1, ECT2, TIAM2, FARP1, ARHGEF12 and BCR in primary cancer was significantly higher than those in normal tissues." (PMID 32029704, 2020). "B3GNT7, TIAM2 and TMPRSS3 were all found to promote the proliferation, invasion and migration of cancer cells." (PMID 32385351, 2020). "TIAM2 and its homologue TIAM1 act as RAC GTPases in cell motility, and are involved in cancer cell invasion and metastasis." (PMID 30817801, 2019). "The set of genes proximate to these IS was significantly enriched in two datasets of cancer genes, including cancer drivers (genes such as BRAF, PIK3R1, RELN and TIAM2) suggesting that some koalas may harbour ERVs that could confer increased cancer susceptibility." (PMID 33637755, 2021).
tumor (9 papers, 2018 to 2025). "Accumulating data showed that TIAM2 was involved in some tumor-associated biological processes, including immune response, cell proliferation, apoptosis, motility." (PMID 37393317, 2023). "The functional consequences of increased TIAM2 protein levels in these tumor types will need to be determined in future experimental studies." (PMID 33097743, 2020). "Moreover, the effect of the competition between Microprocessor and NF90 would in turn also affect the expression of the mRNAs hosting the pri-miRNA, which can be tumor suppressors such as Dicer or oncogenes such as TIAM2." (PMID 36362366, 2022). "In addition, TIAM2, a lipid metabolism-related gene, not only enhances the resistance to osimertinib and cell motility in LUAD but also contributes to the polarization of M2-like tumor-associated macrophage (M2-TAM)." (PMID 39440769, 2025). "Importantly, Jiang and coworkers found that TIAM2 could exert a tumor-promoting effect in PC." (PMID 37393317, 2023). "KALRN, MCF2/Dbl, NGEF/EPHEXIN, ARHGEF7/βPix/COOL-1, CDC42EP2, DOCK9, NET1, TIAM2, ABR, PLEKHG5, RhoBTB2 and PREX1 were identified as being increased at the tumour rim." (PMID 33256106, 2020). "Taken together, our single-cell RNA expression analysis affirmed that SELPLG and SH2D2A are differentially regulated in single tumor-infiltrating L1CAM-CAR T cells, suggesting a functional role, while TIAM2, CORO1B and MYH10 do not seem to influence L1CAM-CAR T cell migration." (PMID 41394860, 2025).
heart disease (2 papers, 2020 to 2021). "Notably, circRNAs in DCM are initiated from heart disease–related gene loci, which include the Rt-circRNAs produced from exons of two different neighboring genes, such as Rt-circRNA from SCAF8 and TIAM2, which very likely tend to bind with heart disease–related miRNA." (PMID 34977015, 2021). "Specifically, rt-circRNAs from SCAF8 and TIAM2 were observed to be dysregulated in DCM and these rt-circRNAs have the potential to sponge multiple heart disease-related miRNAs." (PMID 33160353, 2020).
kidney disease (1 paper, 2024). "Therefore, we hypothesized that the TIAM2-associated variant identified in this population potentially contributes to regulating kidney function or pathogenesis of kidney disease." (PMID 38347632, 2024). "Furthermore, according to the Harmonizome database, there appears to be a functional connection between TIAM2 and kidney disease." (PMID 38347632, 2024).
TIAM2 also shares sentences with these, for which no sentence is quoted: lung adenocarcinoma (3 papers); gastric cancer (2); autism (1); bladder cancer (1); cervical cancer (1); endometrial tumors (1); esophageal squamous cell carcinoma (1); infection (1); lymph node metastasis (1); lymphoma (1); neurodevelopmental disorder (1); non-small cell lung carcinoma (1); osteosarcoma (1); ovarian carcinoma (1); retinoblastoma (1); schizophrenia (1).